MIR522 (microRNA 522)
Synonyms: hsa-mir-522; MIRN522; mir-522
Gene: MicroRNA gene on chromosome 19 (53,751,211 to 53,751,297, forward strand). Ensembl gene ENSG00000283685.
Gene Ontology:
Biological process: miRNA-mediated post-transcriptional gene silencing
Homologues: Orthologues: chimpanzee ptr-mir-522 (100% identical), macaque mml-mir-518e (93% identical). Paralogues in human: MIR518E (92% identical), MIR519A2 (91% identical), MIR523 (90% identical), MIR516A1 (89% identical), MIR520C (89% identical), MIR516A2 (87% identical), MIR518C (87% identical), MIR519C (87% identical), MIR516B1 (86% identical), MIR518D (86% identical), MIR518F (86% identical), MIR520F (86% identical), and 12 more.
Diseases named in the same sentence as MIR522 in open-access papers:
MIR522 is named in the same sentence as 2 diseases in open-access papers, as found by Europe PMC text mining. Sharing a sentence is not in itself a finding about the gene and the disease.
MIR522 shares sentences with these, for which no sentence is quoted: glioblastoma (1 paper); psychiatric disorder (1).